GPC3 (glypican 3)
Diseases named in the same sentence as GPC3 in open-access papers (continued):
Sharing a sentence is not in itself a finding about the gene and the disease.
tumor (continued). "Clinical trials using glypican-3 (GPC3) as a target are the most common CAT-T treatment for HCC, and its anti-tumor activity and safety have been preliminarily determined; however, most of these trials are phase I trials that require further research and confirmation in larger-scale trials." (PMID 39411719, 2024). "Indeed, knockout or small hairpin RNA (shRNA)-mediated knockdown of PDCD1 enhanced the anti-tumor efficacy of C-type lectin-like molecule-1 (CLL-1)-, mesothelin-, epidermal growth factor receptor (EGFR)-, CD19-, and Glypican-3 (GPC3)- CAR-Ts." (PMID 37046597, 2023). "GPC-3, as a glycoprotein, is mainly present in the serum of HCC patients and plays a role mainly through the regulation of the Wnt signaling pathway, while the expression product of the Wnt gene can promote the growth of various tumor tissues." (PMID 37920165, 2023). "In conclusion, HBP radiomic features were closely associated with GPC3-positive expression, and the combination of age, AFP >400 ng/mL, and non-smooth tumor margin provided an effective way to non-invasively and individually predict GPC3-positive HCC patients." (PMID 37841420, 2023). "The hYP7 mAb does not inhibit HCC tumor cell proliferation as it binds the C-terminal lobe of GPC3, while the N-terminal lobe of GPC3 is involved in Wnt/Frizzle binding, signaling, and HCC proliferation." (PMID 37048069, 2023). "Tumor antigens, for example AFP and GPC-3, can provide reference value for efficacy evaluation." (PMID 36936932, 2023). "Immunization with DC pulsed with sufficient GPC3 and PEG10 long peptides alone could also stimulate tumor-specific T cell response, indicating their high immunogenicity." (PMID 37932427, 2023). "First, to endow NK cells with the ability to specifically target GPC3, the free Gpc3 aptamer must be able to target GPC3+ tumor cells but not control cells." (PMID 37665421, 2023). "GPC3 is generally overexpressed in tumor tissues, including lung cancer, but is almost not expressed in the corresponding normal tissues." (PMID 37965271, 2023). "GPC3 plays a key role in HCC development and tumor cell proliferation and invasion regulation." (PMID 37841420, 2023). "In addition, FNDC4 was negatively correlated with AFP, a tumor marker of HCC, and other cancer-related genes such as AHSA1, GDF1, GPC3 and MDK." (PMID 38021165, 2023). "In this study, we aimed to endow NK cells with the ability to specifically target glypican-3+ tumor cells without producing cell damage or genetic alterations, and further evaluated their therapeutic efficiency." (PMID 37665421, 2023). "Ep-LMS, Vi-LMS and GPC3-LMS could target and identify tumor cells and were distributed mainly on the cell surface." (PMID 36681851, 2023). "We found that Epcam, Gpc3 and Dlk1 were highly expressed in a small percentage of cells ( < 25%) in tumor samples compared to normal control livers although not as remarkably as the erythroid genes (Gata1, Alas2, Rhd, Hba-a1)." (PMID 37414763, 2023). "Furthermore, compared with those of the LC or KC mouse group, the tumor tissues of the KLC mouse group exhibited elevated HCC markers (Cd44, Afp, Gpc3 and Ly6d) (P < 0.001 or P < 0.01)." (PMID 38124228, 2023). "On the other hand, areas associated with the hepatocytic or fibrotic component, including the tumor capsule and fibrosis in the non-tumoral liver, correctly overlapped with Glypican-3 (Figure 4C3) and HepPar-1 staining, respectively (Figure 4C4)." (PMID 37046807, 2023). "LNP-engineered Siglec-GΔITIMs-expressing GPC3-specific CAR-Ms present augmented HCC-specific engulfment of macrophages, subsequently stimulating an adaptive anti-tumour immune response and preventing tumour growth in an orthotopic HCC mouse model." (PMID 37894344, 2023). "For example, alpha-fetoprotein (AFP), Glypican-3 (GPC3), and folate receptor (FR) can be found on the tumor cell surface, but are rarely or not expressed in healthy cells." (PMID 35624643, 2022).
tumor (continued). "Preclinical evaluation of logic-gated GPC3-synNotch-inducible CD147-CAR-T cells to target HCC demonstrated selective cytotoxicity towards dual antigen positive targets without on-target/off-tumour toxicity in a human CD147 transgenic mouse model." (PMID 35158772, 2022). "GPC3 was previously found to be expressed in neuroendocrine small cell carcinomas including MCC, but its association with tumor stage, MCPyV status, or prognosis has not been characterized." (PMID 35937502, 2022). "Combining reduced tumor stiffness and elevated AFP level may provide potentially valuable biomarker for GPC3-targeted immunotherapy." (PMID 36518314, 2022). "Therefore, NPs equipped with an anti-GPC3 antibody can readily interact with the protein and be specific for HCC tumor cells." (PMID 36077433, 2022). "The tumor cells were positive for Hep Par-1, Arginase 1 (ARG1), CD10, Glypican-3 (GPC3), and KRT19." (PMID 35789568, 2022). "In addition, we performed fluorescence-activated cell sorting (FACS) analysis of EPCAM+ cells or GPC3+ cells for three HCC samples with available cryopreserved single-cell suspension, because the two markers were known elevated in tumor cells." (PMID 36476645, 2022). "We found that the β-catenin-TCF4-p300 complex occupies the CEGR/ALCD of GPC3 in the tumor sections of HBL patients, but not in the background regions." (PMID 36551548, 2022). "The analysis of GPC3 expression in the specimens of the fresh biobank using QRT-PCR, immunostaining, and Western blot analyses showed high levels of both GPC3 mRNA and GPC3 protein in the tumor sections of HBL patients compared to the background sections." (PMID 36551548, 2022). "In our study, there was no glypican-3 expression in non-tumour tissues, but membranous or cytoplasmic expression was present in tumour cells in 44/60 (73%) cases (online suppl." (PMID 36589727, 2022). "While GPC3- and telomerase-based vaccines have not provided meaningful clinical results, tumor unique peptide identification through HLA-peptidomics is the more robust and personalized approach for anti-HCC vaccine treatment." (PMID 36551958, 2022). "GPC3 is virtually absent in the normal liver but is highly expressed in the tumor tissues of HCC patients and is detected at an elevated concentration in the serum of the same subjects, whereas it is less represented in the tissues of benign liver disorders." (PMID 35454809, 2022). "We selected PC10 and NCI-H446 cells to represent high GPC3-expressing tumours, with 7.22 × 104 or 7.16 × 104 antigen-binding capacity (ABC) per cell, respectively, and MKN74 and MKN45 cells to represent low GPC3-expressing tumours, with 2.49 × 103 or 4.86 × 103 ABC per cell, respectively." (PMID 36071036, 2022). "In mice experiments (including immunodeficient mice), inhibition of PD-1 expression in GPC3-CAR-T cells enhances their killing effect on tumor cells and dramatically reduces tumor load while protecting themselves from exhaustion in combating native PD-L1-expressing HCC." (PMID 36291802, 2022). "The tumor size in HepG2 and PLC8024 xenograft mice treated with CoG133-CAR T cells were decreased and did not significantly differ from those in xenograft mice injected with GPC3-CAR T or CD133-CAR T cells." (PMID 35879685, 2022). "Some of the vaccine-based immunotherapy strategies include tumor-specific neoantigens vaccine, based on the so-called HEPAVAC project, as well as, peptide vaccines, like the glypican-3 (GPC3) vaccine, which is based on the overexpression of GPC3 on the tumor cell membrane in HCC." (PMID 35629333, 2022). "While these two tumor-associated clusters had gene expression profiles similar to that of the DCN-high tumor cell cluster 5, they did not express HB genes including GPC3, DLK1, and DKK1." (PMID 36008377, 2022). "But in our study, we directly assessed the GPC-3 expression in HCC tumor tissues by MRI features which no need peripheral blood and without radiation." (PMID 36091074, 2022).
tumor (continued). "In addition to expression of the hub genes, we noticed that GPC3 and IGF2 were expressed in 65–75% and AFP in more than 40% of the tumour samples." (PMID 36345011, 2022). "To determine whether Ola reduces the targets of the ph-S675-β-catenin-CEGRs/ALCDs pathway in PDXs, we examined the GPC3 and AFP levels in the tumor tissues of PDXs (n = 6) from three HBL patients treated with vehicle (control) or with Ola." (PMID 36551548, 2022). "Apart from these peptide vaccines, GPC3 DNA vaccines could elicit CTL responses against HCC cell lines, inhibit homogenous tumor growth, and increase the survival rates of xenograft-bearing mice." (PMID 35251989, 2022). "Single-target CAR-engineered T cells such as GPC3-CAR T and CD133-CAR T cells efficiently lysed single-positive tumor cells, and dual-target CAR-engineered T cells such as CoG133-CAR T cells had similar lysis rates against single-positive tumor cells." (PMID 35879685, 2022). "In addition to that several molecular markers of tumor progression like HSP70, CAP2, GPC3, and GS were also expressed in expression profiling." (PMID 36479247, 2022). "In total, 143 of 191 tumors (74.8%) were positive for GPC3 mRNA, whereas normal adult liver tissues were negative, suggesting that GPC3 mRNA can be used as an early tumor marker for HCC." (PMID 36077433, 2022). "In vivo, irradiated NK-92/9.28.z cells were also demonstrated to be enriched at the tumor site and efficiently inhibited the growth of GPC3+ HCC xenografts without severe adverse effects." (PMID 36428748, 2022). "Then, we simultaneously transfected GPC3-CAR mcDNA and CD133-CAR mcDNA into human T cells via electroporation and generated CoG133-CAR T cells that recognized either the GPC3 or CD133 antigen to induce effector T cell killing of the target tumor cells." (PMID 35879685, 2022). "Immunohistochemically, tumor cells were negative for Arg-1, glypican-3 (GPC3), hepatocyte specific antigen (HSA), and positive for synaptophysin (Syn), α-inhibin, and Melan A. The Ki-67 index was 1 %." (PMID 34218806, 2021). "Evaluation of raw gene transcripts per million for key upregulated genes with strong upregulation in tumor and PDX, and prior reported involvement in HB, including GPC3, DLK1, and IGF2, showed robust increase in HB tumor gene expression with further elevated expression in PDX tumors." (PMID 34497364, 2021). "We observed upregulation of GPC3 gene expression, a known marker, in HB tumor relative to background liver and nontumor liver." (PMID 34497364, 2021). "Immunohistochemically, the tumor cells were negative for Arg-1, glypican-3 (GPC3), hepatocyte specific antigen (HSA), epithelial membrane antigen (EMA), CK7, CK19, desmin, HMB45, and chromogranin A (CgA)." (PMID 34218806, 2021). "Studies have shown successful GPC3 targeting for drug delivery to HCC due to its overexpression in the tumor, as opposed to normal and cirrhotic liver, where it is not detected." (PMID 35056937, 2021). "Abundant tissue microarray and immunohistochemistry data suggested that GPC3 (a subtype of HSPG) protein expressed highly in over 70% of HCC tumor samples, but none in normal liver tissue, benign liver disease, liver cirrhosis and hepatitis tissues." (PMID 33726759, 2021). "GPC3 and HMGA2 are upregulated in all tumor clusters compared with background liver." (PMID 34497364, 2021). "Second, the mechanisms by which Arg-1 and GPC-3 promote tumor growth, metastasis, and recurrence in ICC patients were not evaluated in this study." (PMID 34715880, 2021). "Up to now, there has been no report on the relationship between GPC3 and tumor response to irradiation." (PMID 34458143, 2021). "Furthermore, both GPC3 and FAT1 regulated the expression of tumor metastasis-related genes, e.g., Snail, Vimentin, and E-Cadherin." (PMID 33420124, 2021). "Eventually, it is known that B4GALNT1 is a relatively ideal target, but targeting GPC3 and ERBB2 might lead to severe “on-target, off-tumor toxicity” in some tissues." (PMID 34975912, 2021).
tumor (continued). "ERY974, a completely humanized IgG structured antibody, directs T cells to non-immunogenic tumors using expression of GPC3 to confer tumor specificity." (PMID 34922633, 2021). "The expression of GPC3 is relate with tumor size of HCC, which suggest that GPC3 may potentially become an early diagnosis biomarker of HCC." (PMID 34306031, 2021). "Expression of circGPC3 and its host gene, GPC3, were upregulated in the tumor tissue compared to the adjacent non-tumorous liver tissue in both the 47 discovery phase HCC samples and 15 independent cohort HCC samples." (PMID 34199580, 2021). "Although broad clinical applications remain warranted, GPC3-targeted imaging may have the potential to complement the staging of HCC, the identification of the tumor margin during surgery, as well as the monitoring after treatment." (PMID 34359547, 2021). "For seven organs, fewer genes were co-expressed with GPC3 in tumor samples than in non-tumor samples." (PMID 31956905, 2020). "LogCD147-CAR selectively kills dual antigen (GPC3+CD147+), but not single antigen (GPC3-CD147+) positive HCC cells and does not cause severe on-target/off-tumor toxicity in a human CD147 transgenic mouse model." (PMID 32968061, 2020). "Subsequently, is the most essential question is that the absence of GPC3 is not lethal to tumor cells." (PMID 32127929, 2020). "Chimeric antigen receptor T cells (CAR-T): Recent studies of HCC tumor xenografts in mice and in vitro demonstrated that engineered CAR-T cells expressing a GPC3 CAR could eliminate GPC3-positive HCC cells." (PMID 33020428, 2020). "GPC3 co-expression patterns differ between tumor and non-tumor samples according to the organ sampled, moreover, the genes whose expression is correlated with GPC3 are distinct according to organ types, all reflecting the complex role of this gene." (PMID 31956905, 2020). "Other tumor biomarkers have been proposed such as osteopontin (OPN), vascular endothelial growth factor (VEGF), angiopoietin 2 (ANG-2), Golgi protein 73 (Gp-73), insulin growth factor-1 (IGF-1), hepatic growth factor (HGF), Glypican-3 and c-MET among others." (PMID 32492896, 2020). "Therefore, GPC3 is not only a specific biomarker and prognostic factor for HCC, but also a potential target for a variety of tumor treatments." (PMID 32127929, 2020). "We then investigated co-expression patterns of GPC3 in the tumor and non-tumor tissues from different organs." (PMID 31956905, 2020). "Finally, single-cell suspension from tumour tissues was subjected to flow cytometry to assess the liver CSC markers, such as AFP, GPC3, CEA and CD44." (PMID 32203212, 2020). "For example, 192 genes were co-expressed with GPC3 in non-tumor liver samples, whereas no genes were significantly co-expressed with GPC3 in LIHC tumor samples." (PMID 31956905, 2020). "In terms of tumor boundary display, the GPC3 protein is only expressed in tumor tissue but not in liver tissue, so it has the best display effect and can clearly indicate the presence of cancer nests in the paratumor liver tissue." (PMID 32195259, 2020). "For example, 4219 genes are co-expressed with GPC3 in non-tumor esophagus samples, whereas no gene is co-expressed with GPC3 in non-tumor samples from prostate and stomach." (PMID 31956905, 2020). "Lentiviral vectors have been broadly used to generate NK cells expressing CARs with 1st, 2nd and 3rd generation designs which target different tumor antigens including CD19, CD20, TF in TNBC, CD33, CD7, CD22, ErbB2, EpCAM, Glypian-3 (GPC3), CS1, EGFR, B cell maturation antigen (BCMA) and CD4." (PMID 32707982, 2020). "The GPC3 protein and gene expression in serum and tumor tissues of HCCs were higher compared to non-malignant healthy livers." (PMID 33643907, 2020). "GPC3 expression has been reported not to depend on HCC tumor size, suggesting a potential role as an early stage diagnostic HCC biomarker." (PMID 32443747, 2020).
tumor (continued). "Tumor necrosis and viable cell content in the tumor were identified as prognostic markers of disease progression, as were the well-known HCC prognostic markers of disease progression, alpha-fetoprotein and Glypican-3 expression." (PMID 30922327, 2019). "No GPC3 expression can be detected in normal liver tissue, while GPC3 expression significantly increased in tumor tissues of LC." (PMID 31781603, 2019). "A phase I clinical trial to confirm its toxicity is currently underway in which there is no limitation to the cancer type if the primary tumor is GPC3-positive." (PMID 31024850, 2019). "In this study, liver markers (AFP, Hepatocyte, Glypican-3, and GS) and colon markers (CK20, CAD17, CDX2, β-catenin, and SATB2) were used for staining of xenograft-derived tumours, with the result that all markers were either expressed only weakly, or were not express at all." (PMID 31367188, 2019). "The differences are statistically significant, indicating that precancer antiviral therapy decreases MVI occurrence and tumor satellite micronodules, and improve the prognosis of HCC maybe by manipulating the expression of CK18, GPC3 or OPN." (PMID 30778112, 2019). "We observed nothing in this case that suggested the presence of HCC: no HCC components in the tumor; negative immunostaining for Hep-Par1, glypican-3, and AFP; no chronic liver diseases; and normal serum AFP levels." (PMID 29721707, 2018). "As a tumor marker, GPC3 was detected in the serum of 40% of HCC patients, but not in cirrhotic patients." (PMID 30297672, 2018). "As LS174T cells have no GPC3 expression, no significant tumor growth was observed for GPC3-bi treatment." (PMID 29357376, 2018). "Immunohistochemically, the tumor cells were positive for glypican-3 (GPC3) and AFP and negative for CD30." (PMID 29933751, 2018). "Glypican-3 (GPC3) is overexpressed in HCC, and is a useful tumor marker for cancer diagnosis." (PMID 30135409, 2018). "Immunohistochemically, the tumor cells were positive for AFP, GPC3, and SALL4." (PMID 30228922, 2018). "The reason of higher level of metastasis, portal vein tumor thrombi, and tumor number in Twist+ CTC group may be due to EMT progression induced by Glypican-3." (PMID 30046595, 2018). "Furthermore, P. y-GPC3-based vaccination dramatically inhibited Hepa1-6-induced tumor growth in the implanted HCC and prolonged the survival of tumor-bearing mice." (PMID 28445973, 2017). "Particularly, glypican-3 is expressed in squamous cell and invasive urothelial carcinomas; however, it is not a good biomarker for diagnosis using tumour tissues." (PMID 29207682, 2017). "Our study showed that both P.y-WT and P.y-GPC3 infection increased high levels of proinflammatory cytokines, such as IL-2, TNF-α and IFN-γ, which leads to activation of defense response effectors against tumor cells." (PMID 28445973, 2017). "To develop an anti-GPC3 immunotoxin for clinical use, we decided to construct two mPE24-based immunotoxins (HN3-mPE24 and HN3-HN3-mPE24) and compared their properties in cell culture and mouse tumor models." (PMID 27419635, 2017). "Strong albeit focal reactivity for GPC3 and AFP was seen in the yolk sac tumor component." (PMID 26880963, 2016). "Abnormal expression of GPC-3 in HCC tissues was markedly related to poor or moderate differentiation (P < 0.001), hepatitis B virus (HBV) infection (P = 0.004), periportal cancer embolus (P = 0.043), and tumor-node- metastasis staging (P = 0.038)." (PMID 27286460, 2016). "Also tumorigenicity of tumor-initiating HCC cells was impaired via reactive oxygen spieces-p38 pathway and Glypican 3 by DSF." (PMID 27602492, 2016). "GPC3 expression did not correlate with tumor size or differentiation, and this result further confirmed with in vitro and in vivo experiments." (PMID 27259271, 2016). "Post-hoc analyzes revealed that the positivity, and the intensity of staining for GPC3 were statistically significantly increased in high grade tumors regardless of the invasiveness of the tumor." (PMID 25896897, 2015).